CNOT4 (CCR4-NOT transcription complex subunit 4)
Description:
Has E3 ubiquitin ligase activity, promoting ubiquitination and degradation of target proteins. Involved in activation of the JAK/STAT pathway. Catalyzes ubiquitination of methylated RBM15. Plays a role in quality control of translation of mitochondrial outer membrane-localized mRNA. As part of the PINK1-regulated signaling, upon mitochondria damage, ubiquitinates ABCE1 and thereby recruits autophagy receptors to the mitochondrial outer membrane to initiate mitophagy.
Synonyms: NOT4; CLONE243; NOT4H
Tractability: PROTAC: UniProt records ubiquitination sites on it; ubiquitination databases record sites on it; its protein half-life has been measured.
Target class: Enzyme; Transferase
Gene: Protein-coding gene on chromosome 7 (135,361,795 to 135,510,145, reverse strand). Ensembl gene ENSG00000080802.
Subcellular location: Cytoplasm; Nucleus
Pathways (Reactome):
Developmental Biology: M-decay: degradation of maternal mRNAs by maternally stored factors
Metabolism of RNA: Deadenylation of mRNA
Gene Ontology:
Molecular function: protein binding; RNA binding; ubiquitin protein ligase activity; ubiquitin-protein transferase activity; metal ion binding; nucleic acid binding
Biological process: protein autoubiquitination; regulation of megakaryocyte differentiation; ubiquitin-dependent protein catabolic process; nuclear-transcribed mRNA poly(A) tail shortening; protein ubiquitination
Cellular component: CCR4-NOT complex; cytosol; cytoplasm; nucleus
Genetic constraint (gnomAD): Loss-of-function variants: 4 observed, 38.74 expected, observed/expected ratio (o/e) 0.1, 90% interval 0.05 to 0.24. The upper end of that interval is the gene's LOEUF score, 0.24, which puts it in group 1 of 6, group 1 being the genes least tolerant of losing a copy. Missense variants: 390 observed, 601.25 expected, observed/expected ratio (o/e) 0.65, 90% interval 0.6 to 0.7. Synonymous variants: 198 observed, 225.01 expected, observed/expected ratio (o/e) 0.88, 90% interval 0.78 to 0.99.
Homologues: Orthologues: chimpanzee CNOT4 (99% identical), rabbit CNOT4 (99% identical), dog CNOT4 (99% identical), pig CNOT4 (99% identical), mouse Cnot4 (98% identical), rat Cnot4 (98% identical), guinea pig CNOT4 (98% identical), macaque CNOT4 (92% identical), tropical clawed frog cnot4 (89% identical), zebrafish cnot4b (75% identical), zebrafish cnot4a (73% identical), Drosophila melanogaster Cnot4 (35% identical), and 1 more.
Diseases named in the same sentence as CNOT4 in open-access papers:
CNOT4 is named in the same sentence as 16 diseases in open-access papers, as found by Europe PMC text mining. Sharing a sentence is not in itself a finding about the gene and the disease. The quoted sentences say what the papers report.
lung carcinoma (2 papers, 2020 to 2023). "To evaluate the correlation between CNOT4 and lung cancer clinically, we assessed the correlation between CNOT4 and overall survival (OS), as well as relapse‐free survival (RFS) using The Cancer Genome Atlas (TCGA) database." (PMID 33034149, 2020). "Here, we identified CNOT4 expression is positively correlated with the overall survival of lung cancer patients, suggesting an inhibitory effect of CNOT4 in lung cancer." (PMID 33034149, 2020). "To further demonstrate the role of CNOT4 in anti‐PD‐1 mediated immunotherapy in lung cancers, we used a tumor‐bearing model, in which control or CNOT4‐overexpression (CNOT4‐OE) A549 cells were subcutaneously implanted into C57BL/6 mice." (PMID 33034149, 2020). "Here, we showed that CNOT4 was positively related to relapse‐free survival and overall survival in lung cancer." (PMID 33034149, 2020). "Taken together, we found that CNOT4 overexpression inhibited tumor growth in vivo, and CNOT4 improved the efficiency of anti‐PD‐1 treatment in lung cancer." (PMID 33034149, 2020). "Our previous data showed CNOT4 was downregulated in lung cancer tissues as comparing with normal tissues." (PMID 33034149, 2020). "Besides, CNOT4 increased cytotoxicity of cytotoxic T lymphocytes (CTLs) to lung cancer cells, suggesting a potential effect of CNOT4 on regulating antitumor immune responses." (PMID 33034149, 2020). "Notably, combination of CNOT4 overexpression and anti‐PD‐1 treatment dramatically inhibited tumor growth, suggesting that CNOT4 overexpression enhanced the effect of anti‐PD‐1 immunotherapy in lung cancer." (PMID 33034149, 2020). "Therefore, CNOT4 and CNOT2 may be stable reference genes for lung cancer cells under these five conditions." (PMID 37274277, 2023). "Overall, these findings indicated that CNOT4 could be a predictor for OS and RFS in lung cancer." (PMID 33034149, 2020).
adenovirus infection (1 paper, 2018). "The levels of at least 2 other members of the complex (CNOT3 and CNOT7) are also reduced during adenovirus infection, whereas the levels of CNOT4 and CNOT1 remain stable." (PMID 29593045, 2018).
dyslipidemia (1 paper, 2025). "Thus, Cnot4 haploinsufficiency mitigates HFD-induced obesity but does not improve dyslipidemia and glucose intolerance." (PMID 40424271, 2025). "In addition, altered mRNA expression of Pgc1a and Igfbp1 may be potentially related to the phenotypes of resistance to obesity but no obvious changes in dyslipidemia and glucose intolerance in Cnot4 Het mice." (PMID 40424271, 2025).
Glucose intolerance (1 paper, 2025). Glucose intolerance (GI) can be defined as dysglycemia that comprises both prediabetes and diabetes. "Elevated hepatic IGFBP1 may have neutralized IGF-1 in the livers of Cnot4 Het mice, leading to hepatic insulin resistance and inhibition of glucose uptake, and eventually augmenting glucose intolerance in Cnot4 Het mice." (PMID 40424271, 2025). "This seems to explain the reason that Cnot4 Het mice under HFD feeding are resistant to obesity but do not improve glucose intolerance and serum lipid levels." (PMID 40424271, 2025). "However, elevated serum lipid levels and glucose intolerance were not improved in Cnot4 Het mice." (PMID 40424271, 2025).
lung adenocarcinoma (1 paper, 2020). A carcinoma that arises from the lung and is characterized by the presence of malignant glandular epithelial cells. "Kaplan–Meier survival analysis demonstrated that CNOT4 is positively associated with both OS and RFS in lung adenocarcinoma patients." (PMID 33034149, 2020).
lung squamous cell carcinoma (1 paper, 2020). "Patients with high CNOT4 expression were accompanied with the significantly higher OS but not RFS in lung squamous cell carcinoma." (PMID 33034149, 2020).
Obesity (1 paper, 2025). Accumulation of substantial excess body fat. "In this study, we generated and analyzed Cnot4 knockout mice and found that Cnot4 heterozygous (Cnot4 Het) mice exhibit resistance to high fat diet-induced obesity, including significant reduction in adipose tissue mass and hepatic lipid depots." (PMID 40424271, 2025). "Since heterozygous knockout of Cnot3 decreases body size and confers resistance to high fat diet (HFD)-induced obesity, we anticipate that Cnot4 heterozygous mice are also resistant to obesity." (PMID 40424271, 2025). "Cnot4 promotes adipocyte differentiation partly through PPARγ, and it likely contributes to hyperplasia in enlargement of adipose tissues during obesity." (PMID 40424271, 2025). "In this study, we demonstrated that heterozygous deletion of Cnot4 in mice attenuates HFD-induced obesity with decreased adipose tissue mass and hepatic fat depots compared with WT mice." (PMID 40424271, 2025). "While several subunits within the CCR4-NOT complex were shown to be involved in obesity and energy metabolism, the roles of CNOT4 in obesity remain unexplored." (PMID 40424271, 2025). "Thus, CNOT4 positively regulates transcriptional activity of PPARγ during adipocyte differentiation in obesity." (PMID 40424271, 2025). "In enlargement of adipose tissues during obesity, Cnot4 heterozygosity may primarily suppresses hyperplasia, which has minimal metabolic impact compared to hypertrophy." (PMID 40424271, 2025). "Thus, while the significance of CCR4-NOT complex in regulating metabolic genes in liver and adipose tissues has been proposed, the roles of CNOT4 in obesity are elusive." (PMID 40424271, 2025). "In this study, we investigated whether Cnot4 regulates high fat diet (HFD)-induced obesity and metabolic disorder." (PMID 40424271, 2025). "The present study shows that Cnot4 Het mice appear resistant to obesity under HFD feeding." (PMID 40424271, 2025). "In addition, despite resistance to obesity in Cnot4 Het mice, serum levels of triglyceride and total cholesterol in Cnot4 Het mice were comparable to those in WT mice, and glucose tolerance test indicated that glucose tolerance was not improved in Cnot4 Het mice." (PMID 40424271, 2025). "Thus, Cnot4 is unlikely to function as a recruiter of mRNAs for CCR4-NOT complex to deadenylate in the context of HFD-induced obesity." (PMID 40424271, 2025).
periodontitis (1 paper, 2022). An acute or chronic inflammatory process that affects the tissues that surround and support the teeth. "Furthermore, 12 hub genes ranked by the top 10% genes with high degree connectivity and five TFs, including SRF, CNOT4, SIX6, SRRM3, NELFA, and ONECUT3, were identified and might play crucial roles in the molecular pathogenesis of periodontitis." (PMID 35397550, 2022).
cancer (7 papers, 2020 to 2025). A tumor composed of atypical neoplastic, often pleomorphic cells that invade other tissues. "Additionally, there may be a relationship between CNOT4 in LIHC cancer, and TAF1 may be associated with SARC cancer." (PMID 40591126, 2025). "Based on our results, we propose CNOT4 as a stable reference gene for expression studies using cancer cell lines HeLa and MDA-MB-231 undergoing serum starvation." (PMID 34593877, 2021). "In conclusion, we propose the use of IPO8, PUM1, HNRNPL, SNW1 and CNOT4 as reference genes in studies comparing gene expression between different cancer and/or normal cell lines." (PMID 34593877, 2021). "Although CNOT4 has been demonstrated to associate with viral RNA replication and transcription regulation, it remains largely unknown whether CNOT4 was involved in cancer development." (PMID 33034149, 2020). "Previous studies have already reported that CNOT4 could suppress cancer progression in cancer." (PMID 39019859, 2024).
tumor (3 papers, 2020 to 2024). "Analysis of the TCGA LIHC cohort indicated that CNOT4 expression level was relatively higher in tumor tissues than normal tissues." (PMID 39019859, 2024). "Consistently, IHC analysis of 5 xenograft tumor tissues showed that CNOT4 protein level was negatively correlated with TNKS1BP1 protein level." (PMID 39019859, 2024). "CNOT4 overexpression suppressed tumor growth in vivo and enhanced the effect of anti‐PD‐1 immunotherapy, which was accompanied by increased CD3+ and CD8+ T lymphocyte infiltration and higher interferon‐γ and tumor necrosis factor‐α levels." (PMID 33034149, 2020). "CNOT4 overexpression decreased the tumor volume and weight, which was consistent with our previous in vitro data." (PMID 33034149, 2020). "In the xenograft model, CNOT4 overexpression restrained tumor growth and enhanced the effect of anti‐PD‐L1 targeted immunotherapy, which was accompanied by more T lymphocyte infiltration and higher lymphokines." (PMID 33034149, 2020). "Our findings demonstrated the significant role of CNOT4 in tumor growth in vivo and the effects of CNOT4 in modulating the sensitivity of anti‐PD‐1 treatment." (PMID 33034149, 2020). "As expected, CNOT4 overexpression inhibited tumor growth and proliferation in vivo, which is consistent with our previous in vitro data." (PMID 33034149, 2020). "Taken together, CNOT4 suppresses the tumor promotion effects of TNKS1BP1 on HCC." (PMID 39019859, 2024). "Finally, we identified the role of CNOT4 in enhancing anti‐PD‐1/PDL‐1 immunotherapy in tumor‐bearing model." (PMID 33034149, 2020). "In conclusion, our findings suggest that CNOT4 functions as a tumor suppressor and could be a combinational target with anti‐PD‐L1/PD‐1 blockage." (PMID 33034149, 2020). "Considering that transcription factors is crucial in regulating tumor vasculogenesis, we integrated and screened the obtained mass spectrometry data, CatRAPID prediction results, the transcription factors set acquired from the Cistrome Data Browser, and CNOT4 targeting proteins." (PMID 39310105, 2024). "We previously reported that CNOT4 may act as a tumor suppressor in NSCLC." (PMID 33034149, 2020). "However, how CNOT4 regulated the activity of T‐cell response to tumor cells is still unclear." (PMID 33034149, 2020).
heart disease (1 paper, 2023). "CNOT4 with insufficient E3 ubiquitin ligase activity has been associated with heart disease showing altered QT interval length." (PMID 37446229, 2023).
infection (1 paper, 2018). The state of being infected such as from the introduction of a foreign agent such as serum, vaccine, antigenic substance or organism. "In contrast to Tab182, the levels of CNOT1 and CNOT4 remained stable throughout the time course of infection." (PMID 29593045, 2018). "Following infection of HeLa cells with either Ad5 or Ad12, levels of CNOT1, CNOT3, CNOT4, and CNOT7 were monitored by Western blotting." (PMID 29593045, 2018).
CNOT4 also shares sentences with these, for which no sentence is quoted: brain tumor (1 paper); hepatocellular carcinoma (1); male infertility (1); tauopathy (1).